TRPA1 (transient receptor potential cation channel subfamily A member 1)
Diseases named in the same sentence as TRPA1 in open-access papers (continued):
Sharing a sentence is not in itself a finding about the gene and the disease.
cancer (continued). "Evidence for TRPA1 as a substrate for ubiquitination by CYLD (an ubiquitin hydrolase and a tumor suppressor gene product) along with wide tissue distribution indicates a probable role in cancer." (PMID 19305786, 2008). "Furthermore, a multitarget cross‐activity may be beneficial in cancer patients treated with chemotherapy that develop a distal peripheral neuropathy, where a contribution of TRPM8, TRPV1, and TRPA1 channels has been reported." (PMID 40123199, 2025). "So far, we do not know whether TRPA1 expression is different in tumours than in non-tumoral samples for other cancer types, and we do not know whether the expression is related to the clinical parameters of patients." (PMID 39770499, 2024). "Therefore, the bimodal pro- and anti-oncogenic effect of ROS-dependent Ca2+ influx via TRPA1 in cancer cells is not surprising." (PMID 37174661, 2023). "The bimodal effect of the TRPA1-mediated Ca2+ influx on the ability of cancer cells to cope or not with oxidative stress could be appropriately exploited for therapeutic purposes." (PMID 37174661, 2023). "In Section 4, we will specifically address how redox-sensitive TRPA1 activation could either engage non-canonical antioxidant defense programs or induce apoptosis in cancer cells." (PMID 37174661, 2023). "Nonetheless, using Trpa1+ / + and Trpa1- / - animals, we followed tumor progression using B16-F10 cells and assessed isolated CD8 + T cells for respiratory and cytotoxic function with an in depth look on how immunometabolism contributes to cell function during cancer progression." (PMID 34041030, 2021). "However, due to the pleiotropic activity of TRPA1 and TRPV4, the safety profile of channel antagonism should be carefully scrutinized, particularly regarding the impact of this therapeutic strategy on cancer outcome and on the efficacy of cancer treatment." (PMID 33317522, 2020). "Recently, TRPA1 has also been reported to mediate a non-canonical oxidative stress defense program in cancer cells and the upregulation of anti-apoptotic pathways to promote cancer cell survival." (PMID 33076385, 2020). "Moreover, in lung adenocarcinoma cells, a direct interaction of TRPA1 with FGFR2 has been demonstrated, which may regulate the metastatic propensity of the cancer cells." (PMID 30248976, 2018). "Another possibility is that anti-cancer drugs activate TrpA1 via the conserved ankyrin repeat domain (ARD), which consists of a large number of tandem ankyrin repeats located in the N-terminus of all TrpA1 channels and required for normal TrpA1 function including responses to noxious chemicals." (PMID 29084244, 2017). "In addition, TRPA1 is co-expressed with TRPV1, is also activated by oxidized lipids, modulates the activity of TRPV1 and may participate in cancer pain." (PMID 26007300, 2015). "However, topically administered TRPA1 and/or TRPV1 agonists could avoid systemic unwanted effects, and therefore, might provide beneficial treatment potentials on the oral mucosa even against cancer generation and progression." (PMID 35163843, 2022). "Thus, at the present stage, it is not possible to exclude that TRPV4 and/or TRPA1 inhibition may negatively affect cancer progression." (PMID 33317522, 2020). "Therefore, modulation of TRPA1 functions might become a target for prevention or therapy of carboplatin-induced CIPN, which could improve chemotherapy with carboplatin to improve their quality of life and prognosis of cancer patients." (PMID 31277262, 2019). "However, TRPA1 regulation in cancer-induced peripheral neuropathy has not yet been studied." (PMID 30510606, 2017). "Transient receptor potential ankyrin 1 (TRPA1) and vanilloid 1 (TRPV1) receptors are non-selective cation channels that have been of great interest in cancer, as their expression is increased in some malignancies." (PMID 38612571, 2024). "Actually, H2O2-induced Ca2+ influx through TRPA1, but not TRPM2, induces oxidative stress tolerance in cancer cells." (PMID 37478173, 2023).
tumor (61 papers, 2009 to 2025). "From the results obtained from the evaluation of tumour infiltration, we notice that a high expression of TRPA1 in infiltrated B cells or CD8+ T cells underlies a poor prognosis." (PMID 39770499, 2024). "Pharmacological blockade of TRPA1 also reduces DBZ-induced nociception in a tumor-associated pain model." (PMID 31801263, 2019). "Down-regulation was seen for CNTN1, CXCL13, MAOB, PAGE4, PENK, SPOCK3 in CP compared to NP as well as for HSD17B2, SALL1, TRPA1 for tumor-associated bladder stromal cells compared to normal bladder." (PMID 19737398, 2009). "Our results suggest that the damage to mitochondrial structure caused by changes in TRPA1 expression may be critical to the development of oxidative stress resistance in tumor cells." (PMID 35982414, 2022). "The combination of photothermal-induced tumor destruction and the modulation of TRPA1 channel activity resulted in a further potentiation of the anticancer effects, leading to a reduction in off-target effects and minimised damage to healthy tissues." (PMID 40813985, 2025). "In EAC tissue, TRPA1 expression was localised to subpopulations of CAFs surrounding tumours, presumed to be CAF5, whereas GSN was more broadly expressed, localising to both intratumoral fibroblast and lymphocyte populations." (PMID 40640495, 2025). "The generation of heat as a consequence of this process has been demonstrated to directly disrupt tumor cells and to trigger the activation of TRPA1." (PMID 40813985, 2025). "The analysis of tumour infiltration reveals that TRPA1 is highly expressed in the tumour environment, and higher expression in B cells improves overall survival." (PMID 39770499, 2024). "In the case of mouse OS samples, seen as a similar osteoid mass, apparently the same level of expression was observed for both Trpa1 and Trpv1 in tumor cells." (PMID 38612571, 2024). "Because these cellular processes are also pathways in the onset or development of tumours, studying TRPA1 in tumorigenesis was just an intuitive step." (PMID 39770499, 2024). "Using TIMER, we determined the Spearman correlation between TRPA1 expression levels and tumour purity." (PMID 39770499, 2024). "We noticed a positive correlation between TRPA1 and ANK1, a membrane-associated cytoskeletal protein, in GBM, KICH, KIRC, LUSC, READ and THYM tumours." (PMID 39770499, 2024). "We examined the relationship between TRPA1 expression and tumour samples, which indicated a high expression in our previous analyses." (PMID 39770499, 2024). "On the other hand, TRPA1 inhibition reduces tumor growth and improves sensitivity to chemotherapies." (PMID 37755210, 2023). "This cluster bomb co-loaded doxorubicin and TRPA1 inhibitor AP-18 (DA-tMN), targeting the deepest tumor sites where ROS are supposed to be elevated." (PMID 37755210, 2023). "We also demonstrate that both TRPV1 and TRPA1 channels are sensitized to tumor-secreted factors in vitro." (PMID 37111275, 2023). "TRPA1 induces Ca2+ influx in response to ROS generated in the inner cells of tumor spheroids and protects them from apoptotic death." (PMID 37039840, 2023). "Regarding the action of chemotherapeutic drugs on TRPA1, it has been shown that channel inhibition decreases tumor growth and increases sensitivity to carboplatin in vivo." (PMID 37755210, 2023). "Early work showed that the TRPA1 protein was upregulated in several cell lines and in tumor samples of human small-cell lung cancer (SCLC)." (PMID 37174661, 2023). "Previous studies reported that VEGF signaling increases the expression of TRPA1 as well as TRPV1 channels in afferent terminals innervating tumor cells." (PMID 35077502, 2022). "The content of ROS in tumor cells is higher than in normal cells, and the neuronal redox sensing channel TRPA1 can improve the defense ability of tumor cells against ROS." (PMID 36185243, 2022).
tumor (continued). "Our results indicate that the increase in intracellular TRPA1 levels can significantly increase the ability of TMZ to damage tumor cells through ROS generation." (PMID 35982414, 2022). "Accordingly, we found that Trpa1-/- CD8+ T cells were more effective in killing tumor cells in vitro and in vivo, which highlights the importance of these immunometabolic modulatory changes exerted to immune cell function." (PMID 34041030, 2021). "To determine the relative levels of circulating immune cells in the Trpa1+/+ and Trpa1-/- mice, we used an automated hemocytometer to evaluate the main cellular components of the circulating blood after tumor inoculation." (PMID 34041030, 2021). "While differences exist between these two studies, both suggest that tumor-induced pain is related to TRPA1." (PMID 35295475, 2021). "We also found increased expression of Il-1β, Il-6, and Ifn- γ in tumor stroma from Trpa1-/- group compared to wild type animals." (PMID 34041030, 2021). "The number (amount) of intratumoral and peritumoral M2 MΦs and 4-HNE staining progressively increased with tumor severity, while TRPA1 expression was similar in all samples." (PMID 34831352, 2021). "On the 17th day, we found a reduction trend in tumor volume in Trpa1-/- compared to Trpa1+/+ animals." (PMID 34041030, 2021). "After inoculation with B16-F10 cells, the tumor was visible from the 13th day onwards in both Trpa1+/+ and Trpa1-/- mice." (PMID 34041030, 2021). "In one group, five rats were injected intravenously with A967079 (one of the TRPA1 inhibitors, 10 mg/kg 10 ul) on day 7 (T7) to detect the short-term effect of antagonistic TRPA1 on hyperalgesia induced by a tumor." (PMID 35295475, 2021). "On the 22nd day, the difference became even more evident and statistically significant, i.e., the tumor volume and weight were significantly reduced in Trpa1-/- mice compared to Trpa1+/+ animals." (PMID 34041030, 2021). "Using Trpa1+/+ and Trpa1-/- animals, we evaluated tumor progression using murine B16-F10 cells and assessed isolated CD8+ T cells for respiratory and cytotoxic functions." (PMID 34041030, 2021). "TRPA1 staining was identified mainly at the cytoplasmic level, although the proportion of cells that expressed protein was variable across the tumor sections analyzed, ranging from 5% to 90%." (PMID 33076385, 2020). "TRPA1 both enhances tumor growth and reduces chemo-sensitivity through mediating calcium influx dependent anti-apoptotic pathways." (PMID 32211326, 2020). "The nociceptive ion channel transient receptor potential ankyrin (TRPA1) was up-regulated in DRGs by several painful CM samples (Painful Tumor 2 p = 0.04, Painful Tumor 3 p = 0.05) as was interleukin 1β (Painful Tumor 1)." (PMID 31511601, 2019). "Of note, the activation of TRPA1 in SCLC cells can promote cell survival suggesting a potential role in tumor progression." (PMID 30248976, 2018). "In the case of TRPA1, it has been shown that tumor-relevant compounds like cigarette smoke or DNA-damaging electrophiles can activate this channel." (PMID 30248976, 2018). "Below, activators of TRPA1, especially with tumor-biological relevance, will be discussed in more detail." (PMID 30248976, 2018). "Tissues were collected from the dorsal root ganglia (DRGs) to quantify the pain-recognition receptor, TRPA1, in parallel with the marker of tumor progress and the pain transducer, CGRP, and to study the underlying molecular mechanisms." (PMID 30510606, 2017). "The concurrent expression of CGRP by TRPA1 +IR neurons increases with continuous tumor growth and neuronal damage." (PMID 30510606, 2017). "However, TRPA1 correlates negatively with tumour purity, indicating a higher expression in the microenvironment." (PMID 39770499, 2024). "Our results indicate that the activation of TRPA1 is an important regulatory signal for NK cells, and agonists of TRPA1 could be used to strengthen the tumor response of the immune system." (PMID 37834182, 2023).
tumor (continued). "In these cells, TRPA1 activation promoted tumor cell survival and growth." (PMID 37240443, 2023). "From this study, TRPA1 emerged as a tumor-suppressor protein and its activation may be helpful for better therapy." (PMID 37507867, 2023). "Nevertheless, if TRPA1-induced ROS production rather facilitates tumor progression, the therapeutic efficacy of this approach could be hampered by a negative-feedback mechanism." (PMID 37174661, 2023). "ROS generation is crucial to induce anoikis, but TRPA1 activation underlay detachment-induced Ca2+ signals and anoikis resistance in the inner region of tumor spheroids without reducing intracellular ROS levels." (PMID 37174661, 2023). "ROS released by infiltrating M2 macrophages may target TRPA1-expressing melanoma cells to amplify oxidative stress signals that affect tumor cell survival and proliferation." (PMID 37039840, 2023). "Furthermore, previous results from our group showed that the removal of Trpa1 channel results in reduced tumor growth via increased CD8+ cytotoxicity." (PMID 35562405, 2022). "Therefore, we used TRPA1-overexpressing and shRNA U251 cells to directly observe changes in tumor cells when TRPA1 expression is increased." (PMID 35982414, 2022). "During the growth of tumor cells, TRPA1 acts as a critical mediator in tumor angiogenesis." (PMID 36278189, 2022). "TRPA1 is highly expressed in tumor tissues, especially in tumor fibroblasts." (PMID 36278189, 2022). "Moreover, even though TRPA1 has been associated with the control of growth, survival, and activation of neutrophils, macrophages, B and T cells, the roles of this channel upon the metabolic regulation of T lymphocyte activation remain unclear, especially in the tumor microenvironment." (PMID 34041030, 2021). "Within this line, our data suggest that TRPA1 could be an important player in modulating T-dependent responses in the tumor microenviroment." (PMID 34041030, 2021). "The relative levels of both perforin (Prf1) and granzyme (Gsmf) observed in the tumor stroma were highly upregulated in the Trpa1-/- group, supporting the fact that in this group the CD8+ T cytotoxic effector function was more prevalent that in the wild type group." (PMID 34041030, 2021). "The novel finding of TRPA1 expression in SSs may open a discussion on its role as a player in the genesis and development of this aggressive tumor and, given the uncertainty of the mechanism, to the premonitoring of peculiar pain symptoms." (PMID 33076385, 2020). "TRPA1 expression has been shown to be highest in the mentioned tumour types, and it remains to be clarified whether the described mechanisms apply to other tumours." (PMID 31547502, 2019). "This led to increased oxidative stress tolerance, and TRPA1 inhibition could reduce tumour growth and enhance chemotherapy sensitivity in xenograft models." (PMID 31547502, 2019). "Thus, our findings not only identify the regulatory function of TRPA1 ankyrin repeats, but also highlight the importance of ankyrin–proline interactions in tumor progression." (PMID 29038531, 2017). "Our study also suggests that topical application of selective TRPA1 antagonist might be potentially used to counteract HQ-induced skin irritation." (PMID 28790335, 2017). "Furthermore, TRPA1 inhibition attenuates xenograft tumor growth and increases chemosensitivity." (PMID 37892239, 2023). "Thus, our study of TRPA1 protein expression in SSs may gain new insights on the biology of this tumor." (PMID 33076385, 2020). "In this context, a novel approach to tumor therapy has been suggested, namely the utilisation of near-infrared (NIR) light-responsive polymer nanoparticles (CPNs) conjugated with TRPA1 inhibitors." (PMID 40813985, 2025). "We investigated the mRNA levels of TRPA1 using TIMER.2 analysis, which investigates tumour and normal samples from the TCGA project." (PMID 39770499, 2024).
tumor (continued). "However, since function of the TRPA1 channel was found to be an important chemosensor for pain-eliciting substances or potentially harmful irritants, it was also found that TRPA1 may exert tumor-promoting effects." (PMID 37511605, 2023). "We found significantly higher expression levels of TRPA1, TRPM8, and TCAF1/F2 in tumoral tissues compared to normal tissues, but lower expression levels of TRPV6, suggesting that TRP channels have either tumor-suppressive or oncogenic roles." (PMID 36012311, 2022). "Even some approved drugs or novel drugs in clinical trials are available, which modulate some potentially tumor-relevant TRP channels, e.g., GRC 17536 (TRPA1), XEN-D0501 (TRPV1), SB705498 (TRPV1)." (PMID 30248976, 2018). "The upregulation of TRPA1 and CGRP and the proliferation of the nuclei as a response to the growing tumor were confirmed by the relative counting of the +IR cells." (PMID 30510606, 2017). "TRPA1 expression was observed in CAF5 cells from either treated or naïve samples and IHC confirmed expression in stromal regions (likely to be CAFs) adjacent to tumour cells." (PMID 40640495, 2025). "Negative and significant correlations between TRPA1 expression and tumour purity were found for COAD (p = 8.04 × 10−3), LUAD (p = 2.28 × 10−7) and PRAD (p = 0.37 × 10−7)." (PMID 39770499, 2024). "It is unclear why TRPA1 activation evoked pro-oncogenic repetitive Ca2+ spikes in some, e.g., breast and lung, but not all tumor types that have been examined so far." (PMID 37174661, 2023). "The role of TRPA1 in non-neuronal cells is still not clarified, but results from tumor cells suggest that TRPA1 activation is a protective mechanism to counteract oxidative stress." (PMID 36614296, 2023). "TRPA1 gene expression was higher in normal tissues vs. tumoral tissues (p = 3.15 × 10−1), in tumor tissues vs. metastatic tissues (p = 2.02 × 10−4), and in normal vs. metastatic tissues (p = 2.70 × 10−4)." (PMID 36012311, 2022). "TRPA1, TRPV2, and TRPC3 were shown to be up-regulated in three different endothelial cell lines established from PCa patients as well as in endothelial cells lining tumor capillaries in vivo." (PMID 36430727, 2022). "Recently, Antoniazzi and colleagues showed that tumor growth, through injection of B16-F10 cells in the mouse paw, is not different between Trpa1+/+ and Trpa1-/- genotypes, which contrasts with our results." (PMID 34041030, 2021). "Previous studies showed that AITC diminished the viability and inhibited the migration of tumour cells through a mechanism that was not related to TRPA1 activation." (PMID 33479347, 2021). "Finally, we discuss the role of endothelial TRP channels in aberrant tumor vascularization by focusing on TRPC1, TRPC3, TRPV2, TRPV4, TRPM8, and TRPA1." (PMID 32038296, 2019). "We treated mouse DRG neurons with painful tumor CM or non-painful tumor CM for 48 hours, then performed Ca2+ imaging during challenge with the TRPA1 agonist cinnamaldehyde (200 μM)." (PMID 31511601, 2019). "Our previous studies have shown that the TRPA1 gene encoding the channel as well as the protein is over-expressed in PDAC cells and patient-derived tissues compared to non-tumoral cell lines or tissue adjacent to the tumor." (PMID 38543130, 2024). "Additionally, TRPA1 can be activated by O2, H2O2, and platinum drugs such as carboplatin and oxaliplatin, which are widely known clinically used cytotoxic drugs, and promote the cellular oxidative stress defense process resulting from tumor cells escaping ROS." (PMID 36090899, 2022). "Since differences in TAM populations did not seem to account for the delayed tumor progression in Trpa1-/- mice, we further investigated if this might be due to the difference observed in circulating lymphocytes." (PMID 34041030, 2021).